IGHV2OR16-5 (immunoglobulin heavy variable 2/OR16-5 (non-functional))
Synonyms: IGHV2/OR16-5; IGHV2OR165
Gene: Immunoglobulin variable (V) gene on chromosome 16 (32,847,713 to 32,848,156, forward strand). Ensembl gene ENSG00000259303.
Gene Ontology:
Molecular function: antigen binding
Biological process: immunoglobulin mediated immune response
Cellular component: extracellular region; plasma membrane
Homologues: Orthologues: mouse Ighv8-12 (66% identical), mouse Ighv8-6 (65% identical), mouse Ighv8-5 (64% identical), mouse Ighv8-8 (63% identical), mouse Ighv8-9 (63% identical), rat AABR07065813.1 (63% identical), mouse Ighv8-11 (61% identical), mouse Ighv8-2 (59% identical), mouse Ighv8-13 (57% identical), mouse Ighv8-4 (56% identical), rat Igh-6-ps1 (47% identical). Paralogues in human: IGHV2-26 (88% identical), IGHV2-70D (85% identical), IGHV2-70 (84% identical), IGHV2-5 (82% identical), IGHV4-59 (53% identical), IGHV4-61 (53% identical), IGHV4-39 (52% identical), IGHV4-28 (50% identical), IGHV4-31 (50% identical), IGHV4-4 (50% identical), IGHV4OR15-8 (50% identical), IGHV4-34 (49% identical), and 65 more.